RASAL2 (RAS protein activator like 2)
Description:
Inhibitory regulator of the Ras-cyclic AMP pathway.
Synonyms: NGAP
Tractability: Antibody: the Human Protein Atlas places it where antibodies can reach. PROTAC: ubiquitination databases record sites on it; its protein half-life has been measured.
Gene: Protein-coding gene on chromosome 1 (178,093,768 to 178,484,147, forward strand). Ensembl gene ENSG00000075391.
Subcellular location (Human Protein Atlas): Focal adhesion sites; Plasma membrane
Pathways (Reactome):
Signal Transduction: RND1 GTPase cycle; RND3 GTPase cycle; Regulation of RAS by GAPs
Gene Ontology:
Molecular function: protein binding; GTPase activator activity
Biological process: regulation of intracellular signal transduction; signal transduction; adipose tissue development; gene expression; multicellular organism growth; regulation of protein activation cascade; response to dietary excess; response to glucose
Cellular component: cytosol
Genetic constraint (gnomAD): Loss-of-function variants: 52 observed, 118.77 expected, observed/expected ratio (o/e) 0.44, 90% interval 0.35 to 0.55. The upper end of that interval is the gene's LOEUF score, 0.55, which puts it in group 2 of 6, group 1 being the genes least tolerant of losing a copy. Missense variants: 1,291 observed, 1,577.2 expected, observed/expected ratio (o/e) 0.82, 90% interval 0.78 to 0.86. Synonymous variants: 536 observed, 574.53 expected, observed/expected ratio (o/e) 0.93, 90% interval 0.87 to 1.
Homologues: Orthologues: chimpanzee RASAL2 (99% identical), macaque RASAL2 (99% identical), guinea pig RASAL2 (98% identical), pig RASAL2 (98% identical), mouse Rasal2 (97% identical), rat Rasal2 (97% identical), dog RASAL2 (95% identical), tropical clawed frog rasal2 (84% identical), zebrafish rasal2 (72% identical), Caenorhabditis elegans gap-2 (27% identical), Drosophila melanogaster raskol (18% identical), Drosophila melanogaster RasGAP1 (13% identical), and 1 more. Paralogues in human: DAB2IP (53% identical), RASAL3 (25% identical), RASAL1 (15% identical), NF1 (15% identical), RASA3 (15% identical), RASA4 (14% identical), RASA4B (14% identical), RASA2 (12% identical), RASA1 (11% identical).
Diseases named in the same sentence as RASAL2 in open-access papers:
RASAL2 is named in the same sentence as 38 diseases in open-access papers, as found by Europe PMC text mining. Sharing a sentence is not in itself a finding about the gene and the disease. The quoted sentences say what the papers report.
breast carcinoma (16 papers, 2014 to 2025). "Although RASAL2 is rarely mutated in breast cancer, its expression is reduced due to promoter methylation in about 50% of luminal B tumors, where it is associated with reduced disease-free survival (DFS) and overall survival (OS)." (PMID 36358725, 2022). "Nearly 25% of luminal B tumors, the most aggressive form of breast cancers exhibits a concomitant loss of RASAL2." (PMID 34966481, 2021). "The most common cancer that is associated with RASAL2 is breast cancer, such as luminal B breast cancer." (PMID 31799194, 2019). "In a luminal B mammary tumor mouse model, the loss of RASAL2 enhanced metastasis and, using this model, 60% of primary tumors spontaneously lost DAB2IP, which also increased metastasis." (PMID 31799194, 2019). "Down-regulation of RASAL2 expression is observed in primary human breast cancer and is associated with recurrence and metastasis." (PMID 25216515, 2014). "Moreover, in a luminal model of breast cancer, RASAL2 mutations promoted metastasis and correlated with recurrence and poor overall survival of patients with luminal B cancers." (PMID 28182001, 2017). "Intriguingly, they found that RASAL2 is frequently silenced together with DAB2IP in high-grade luminal B breast cancers." (PMID 38902547, 2024). "As a member of RAS GTPase-activating protein family (RAS-GAP), RAS protein activator like 2 (RASAL2) was first reported as a tumor suppressor and down-regulated in different types of tumors, e.g., luminal B breast cancer, lung cancer, and ovarian cancer 5-12." (PMID 35844783, 2022). "RASAL2 is a reported tumour suppressor in luminal B breast cancer, ovarian cancer, pancreatic ductal carcinoma, nasopharyngeal carcinoma and malignant astrocytoma." (PMID 35668070, 2022). "Traditionally, RASAL2 functions as a tumor suppressor in lung cancer, ovarian cancer, pancreatic cancer, bladder cancer and luminal B breast cancer." (PMID 34966481, 2021). "On the other hand, tumor suppressor role has been described for RASAL2 in a number of cancer types including luminal B breast cancers; renal cancers; bladder cancer; astrocytoma’s; nasopharyngeal cancer; pancreatic cancer; ovarian cancer and lung cancer." (PMID 34966481, 2021). "Our observation is consistent with previous report of tumor suppressor function for RASAL2 in breast cancer and colorectal cancer." (PMID 34966481, 2021). "The combined loss of RASAL2 and DAB2IP in a subset of luminal B breast cancers results in epithelial–mesenchymal transition (EMT)." (PMID 31799194, 2019). "It was reported that RASAL2 acts as a tumor suppressor when it was found that RASAL2 was downregulated in luminal-B breast cancer in one of the earliest studies." (PMID 31799194, 2019). "Especially, the controversial effects of RASAL2 in breast cancer development have been reported, indicating its role as a double-edged sword in certain condition." (PMID 28182001, 2017). "RASAL2 is a GTPase activating proteins (GAPs) which was recently reported as a tumor suppressor in breast cancer." (PMID 25216515, 2014). "Using an independent patient cohort of TNBC/BRCA-mutant breast cancer patients, we found that transcripts of RASAL2 variant 2, but not variant 1, was significantly upregulated following treatment." (PMID 39890967, 2025). "For examples, in luminal B breast cancer, lung adenocarcinoma, ovarian cancer, nasopharyngeal carcinoma and bladder cancer, RASAL2 inhibits tumor cell migration and invasion by suppressing RAS signaling pathway and epithelial mesenchymal transition (EMT) 8, 9, 22-24." (PMID 35844783, 2022). "Furthermore, RASAL2 cooperates with other RasGAPs to suppress transformation and metastasis indicating tumor suppressor function for RASAL2 in breast cancer." (PMID 34966481, 2021). "It was recently reported that RASAL2 functions as a tumor suppressor in breast cancer." (PMID 25216515, 2014).
breast carcinoma (continued). "In breast cancer, Cichowski and colleagues found that DAB2IP cooperates with another RasGAP family member, RASAL2, to limit metastasis in ER+ breast cancer." (PMID 38902547, 2024). "Moreover, to be consistent with the previous studies reported in luminal breast cancer and ovarian cancer, we also observed that RASAL2 could modulate BCa cells stemness and EMT via MAPK pathway, in which the transcription factor SOX2 acted as an important bridge." (PMID 28182001, 2017). "While alterations of RAS/RAF/MEK/ERK genes are rare in breast cancer, ERK pathway activation may arise from alterations in upstream regulators, such as the RasGAPs NF1 and RASAL2." (PMID 36358725, 2022). "Notably, promoter hypermethylation of RASAL2 and DAB2IP was identified in aggressive luminal B breast cancer." (PMID 31627186, 2019). "RASAL2, a unique RAS GTPase-activating protein (RAS-GAP), has been reported as a tumor-suppressor gene, which inhibits tumor progression in different types of cancer, such as luminal B breast cancer, ovarian cancer, lung cancer, nasopharyngeal carcinoma, and colorectal cancer." (PMID 30158581, 2018).
colorectal cancer (12 papers, 2018 to 2025). A primary or metastatic malignant neoplasm that affects the colon or rectum. "In colorectal cancer, RASAL2 interacts with Hippo regulator LATS2, preventing YAP from degradative ubiquitination and thereby enabling its oncogenic function as a nuclear transcription co-factor." (PMID 39890967, 2025). "Depending on the cellular context and type of stimulation, RASAL2 can have pro- or anti-tumorigenic effects and is involved in tumor progression in colorectal cancer." (PMID 39272991, 2024). "It promotes colorectal cancer progression via the hippo pathway, and the knockdown of RASAL2 inhibits the growth and invasion of hepatocellular carcinoma cells." (PMID 36159573, 2022). "This gene has been identified as a functional tumor suppressor, and downregulation of the RASAL2 protein has been reported in various cancers, e.g. lung, breast, bladder, and colorectal cancer." (PMID 35308102, 2022). "Human herpetic virus 8 (HHV-8) binds to IPO5mRNA, leading to Kaposi's sarcoma; IPO5 mediates RASAl2 nuclear transport to accelerate the colorectal cancer cells proliferation and migration." (PMID 36120598, 2022). "However, the oncogenic roles of RASAL2 were reported recently in some solid tumor such as colorectal cancer, liver cancer and triple-negative/estrogen receptor-negative breast cancer 14-18." (PMID 35844783, 2022). "RASAL2 can also promote the progression of colorectal cancer through the LATS2 / YAP axis." (PMID 34430085, 2021). "Traditionally, RASAL2 has been regarded as a tumor suppressor but recent studies have found that it is an oncogene in specific types of cancer, such as colorectal cancer, liver cancer, triple-negative breast cancer, triple-negative/estrogen receptor-negative breast cancer." (PMID 31799194, 2019). "Paradoxically, RASAL2 is also an established oncogene in aggressive cancer types such as TNBC, pancreatic ductal adenocarcinoma, colorectal cancer and gastric cancer." (PMID 39890967, 2025). "In colorectal cancer (CRC), RASAL2 is overexpressed and RASAL2 nuclear transportation is mediated by importin-5 (IPO5) to promote proliferation and tumorigenicity." (PMID 31799194, 2019). "In triple negative breast cancers, liver cancer and colorectal cancer RASAL2 has been observed to promote carcinogenesis." (PMID 34966481, 2021).
triple-negative breast carcinoma (12 papers, 2018 to 2025). An invasive breast carcinoma which is negative for expression of estrogen receptor (ER), progesterone receptor (PR), and human epidermal growth factor receptor 2 (HER2). "In triple-negative breast cancer, CREB was identified as a key transcription factor regulating RAS protein activator-like 2 (RASAL2), a crucial factor associated with resistance to platinum-based chemotherapy." (PMID 40860181, 2025). "For example, we have recently found that the promotion of BCL-2 transcription by CREB, induced via a YAP-RASAL2 axis, underpins the mechanism of RASAL2-driven chemoresistance in triple-negative breast cancer (TNBC)." (PMID 40157009, 2025). "Yet, other studies have reported RASAL2 to have oncogenic activity in triple negative breast cancer and human hepatocellular carcinoma." (PMID 34966481, 2021). "A previous study reported that miR-136 suppressed the epithelial-to-mesenchymal transition of cancer cells by regulating the RAS protein activator like 2 (RASAL2) gene in triple-negative breast cancer." (PMID 33562573, 2021). "In vitro, CRNDE controls hsa-miR-136-5p level which, in turn, is able to target RASAL2 and Wnt/beta-catenin signaling in triple-negative breast cancer cells." (PMID 31146345, 2019). "A genome-wide study revealed that RASAL2 depletion inhibits cancer cell growth and invasiveness in liver and triple-negative breast cancers." (PMID 30037330, 2018). "In addition, RAS protein activator like 2 (RASAL2), a RasGAP gene, promotes the progression of triple-negative breast cancer through the activation of RAS-related C3 botulinum toxin substrate (RAC1)." (PMID 33801965, 2021). "RASAL2 is a target of anti-invasion miR-136 and miR-203 in triple-negative breast cancer (TNBC)." (PMID 31799194, 2019). "RASAL2 also activates RAC1 to promote triple-negative breast cancer progression." (PMID 33817145, 2019). "However, other studies observed an upregulation of RASAL2 in triple-negative breast cancer and hepatocellular carcinoma." (PMID 30158581, 2018). "However, one report has characterized RASAL2 as oncoprotein in triple negative breast cancer." (PMID 34966481, 2021). "In addition, activation of the RASAL2/ARHGAP24/RAC1 module slows triple-negative breast cancer (TNBC) progression, and RASAL2 overexpression is related to poor prognosis and tumor recurrence in TNBC." (PMID 36159573, 2022).
lung cancer (9 papers, 2017 to 2022). A malignant neoplasm involving the lung. "Low expression of RASAL2 can promote EMT in lung cancer and promote metastasis through the RAS /ERK pathway, which is inconsistent with our results." (PMID 34430085, 2021). "Subsequently, several studies reported that RASAL2 also decreased in various types of cancer, such as ovarian cancer, lung cancer, nasopharyngeal carcinoma, and colorectal cancer." (PMID 30158581, 2018). "RASAL2 inactivation could promote lung cancer cell migration and lung metastasis in nude mice by inducing epithelial‐mesenchymal transformation." (PMID 36420686, 2022). "In lung cancer, previous studies seem to indicate that RASAL2 is a tumor suppressor." (PMID 34430085, 2021). "RASAL2 was initially identified as a tumor suppressor and the inactivation of RASAL2 promoted tumor progression and metastasis in luminal B breast, ovarian, and lung cancers." (PMID 30037330, 2018).
ovarian carcinoma (9 papers, 2014 to 2022). A malignant neoplasm originating from the surface ovarian epithelium. "In ovarian cancer, RASAL2 was downregulated, especially in patients with advanced stages and grades." (PMID 31799194, 2019). "In the current study, PD98059, also a MEK inhibitor, efficiently attenuated the intensity in the invasive and migration, anchorage-independent growth and EMT induced by RASAL2 suppression in ovarian cancer cells." (PMID 25216515, 2014). "RASAL2 knockdown in ovarian cancer cell lines promoted in vitro anchorage-independent growth, cell migration and invasion and in vivo tumor formation." (PMID 25216515, 2014). "Again, phospho-MEK1/2 displayed clear up-regulation in ovarian cancer cell lines after RASAL2 depletion." (PMID 25216515, 2014). "RASAL2 was down-regulated in ovarian cancer samples compared with normal tissue samples, especially in advanced stages and grades." (PMID 25216515, 2014). "Invasion and migration capabilities of ovarian cancer cell lines were significantly enhanced following RASAL2 suppression." (PMID 25216515, 2014). "Taken together, these results confirm the oncogenic role of RASAL2 down-regulation in ovarian cancer, especially its effects on invasion and migration." (PMID 25216515, 2014). "We found that the expression of RASAL2 is down-regulated in ovarian cancer, and this down-regulation is related to clinical features." (PMID 25216515, 2014). "To delineate the extent of RASAL2 expression alterations in ovarian cancer, we analyzed RASAL2 expression by qRT-PCR in cDNA from 57 patients representing all stages and grades of the disease and 8 normal ovarian epithelium samples." (PMID 25216515, 2014). "To further verify the oncogenic role of RASAL2 knockdown, we established ovarian carcinoma orthotopic mouse models using the SK-OV-3 cell line to mimic orthotopic implantation metastases." (PMID 25216515, 2014). "We propose RASAL2 as a potential therapeutic target and prognostic marker for ovarian cancer; however, further evaluation is still required." (PMID 25216515, 2014). "To functionally validate the role of RASAL2 in ovarian cancers, we suppressed the expression of RASAL2 in ovarian cancer cell lines (SK-OV-3, OVCAR3 and A2780) using short-hairpin RNAs (shRNA), which targeted 2 different sequences in RASAL2." (PMID 25216515, 2014). "The mRNA expression levels of RASAL2 and E-cadherin were evaluated in 57 patients ovarian cancer and 8 normal ovarian epithelium samples by quantitative RT-PCR." (PMID 25216515, 2014). "In summary, we show that RASAL2, which is down-regulated in ovarian cancer, is a novel suppressor of EMT and metastasis, and its regulation of EMT and metastasis relies on activation of the Ras-ERK pathway." (PMID 25216515, 2014). "Following RASAL2 depletion, ovarian cancer cells showed enhanced invasion and migration, anchorage-independent growth and tumor formation." (PMID 25216515, 2014). "Taken together, these findings show that RASAL2 is down-regulated in primary ovarian cancers, and this decreased expression is correlated with pathological grade and FIGO stage." (PMID 25216515, 2014). "Although the total levels of Raf-1 remained unchanged, ovarian cancer cells transfected with either RASAL2-shRNA1 or RASAL2-shRNA2 showed a clear induction of Raf-1 phosphorylation compared with control cells." (PMID 25216515, 2014). "PD98059 significantly inhibited anchorage-independent colony growth of ovarian cancer cell lines transfected with RASAL2-shRNA1 or-2." (PMID 25216515, 2014). "Taken together, these results indicate that RASAL2 is crucial for ovarian cancer to maintain epithelial characteristics." (PMID 25216515, 2014). "Taken together, these findings indicate that RASAL2 is an essential Ras-ERK pathway regulator in ovarian cancer." (PMID 25216515, 2014).